HNRNPK (heterogeneous nuclear ribonucleoprotein K)
Diseases named in the same sentence as HNRNPK in open-access papers (continued):
Sharing a sentence is not in itself a finding about the gene and the disease.
tumor (125 papers, 2003 to 2026). "Many studies have demonstrated the association between aberrant hnRNPK expression and tumor progression." (PMID 39479349, 2024). "The expression of hnRNPK was significantly increased in GC and its upregulation was associated with tumor stage and metastasis." (PMID 31857793, 2019). "In this study, we demonstrated that the expression of hnRNPK was significantly increased in GC and its upregulation was associated with tumor stage and metastasis." (PMID 31857793, 2019). "It has been shown that dysregulation of HNRNPK is associated with tumor development, progression, and prognosis." (PMID 31942561, 2019). "HNRNPK overexpression and cytoplasmic accumulation in several tumors were associated with tumor progression and poor prognosis." (PMID 29262567, 2017). "Recently, it has been reported that abnormal expression of HNRNPK is associated with tumor formation, development and prognosis." (PMID 29262567, 2017). "hnRNPK was significantly increased in GC and associated with tumor stage and metastasis." (PMID 31857793, 2019). "Our findings demonstrated that circPVT1 promotes tumor progression through dual mechanisms: cP104aa increases c‐MYC expression by forming a complex with HNRNPK, while circPVT1 enhances c‐MYC expression by binding to the EIF4A3 protein." (PMID 40966379, 2025). "The association was likely to enhance tumor-cell migration and invasion during tumor development by altering HNRNPK expression." (PMID 39925739, 2025). "hnRNPK demonstrates context-dependent multifunctionality, functioning as both a tumor suppressor and an oncogene." (PMID 40775642, 2025). "Functionally, ectopic expression of AKT2-206 conferred MAPKi resistance in sensitive cell lines, while knockdown of hnRNPK enhanced the sensitivity of tumor cells to MAPKi." (PMID 40681872, 2025). "NEAT1 is associated with RBPs like HNRNPK (heterogeneous nuclear ribonucleoprotein K) in various cancers including HNSCC and promotes tumor growth." (PMID 40231344, 2025). "It suppresses tumor progression by promoting hnRNPK ubiquitination and inhibiting the IGF2/PI3K/AKT axis, while its loss activates immunosuppressive cancer‐associated fibroblasts." (PMID 41103217, 2025). "Our study provides a promising biomarker for NSCLC and opens a novel avenue for NSCLC therapy by targeting hnRNPK to prevent the "exosome escape" of tumor-suppressive miR-4732-3p from NSCLC cells." (PMID 38654325, 2024). "There were elevated levels of miR-4732-3p in xenograft tumor tissues, but declined miR-4732-3p expression in serum fucosylated exosomes from nude mice with hnRNPK knockdown." (PMID 38654325, 2024). "Inhibition of HNRNPK increases post-irradiation DNA damage, thereby decreasing the survival of tumor cells." (PMID 39816354, 2024). "hnRNPK promotes the metastasis of tumor cells by interacting with some transcription factors or long noncoding RNAs such as prospero-related homeobox 1 and LINC00941." (PMID 39479349, 2024). "For example, all human granzymes cleave heterogeneous nuclear ribonucleoprotein K (hnRNPK), reducing tumor cell viability." (PMID 38646541, 2024). "The examination of hnRNPK expression patterns across diverse tumor types has provided valuable insights." (PMID 39479349, 2024). "The primary role of hnRNPK is its involvement in cell proliferation and migration, both of which are essential processes for tumor growth and progression." (PMID 39479349, 2024).
tumor (continued). "The number of infiltrative tumor cells in the different treatment groups was compared, revealing that the HNRNPK (K422R) treatment group exhibited a higher number of infiltrative tumor cells at the tumor edge." (PMID 39494331, 2024). "Altogether, we can conclude that Circ-VPS33B promotes tumor growth and the Warburg effect through the miR-873-5p/HNRNPK axis." (PMID 39816354, 2024). "Our findings showed that the knockdown of hnRNPK suppressed tumor growth, as evident from a notable reduction in tumor weight, tumor growth rate, and Ki-67 expression in xenograft tumors." (PMID 38654325, 2024). "In contrast, NSCLC cells preferentially secrete miR-4732-3p via hnRNPK into fucosylated exosomes and discard it extracellularly instead of retaining it intracellularly so as to escape tumor-suppressive effects of miR-4732-3p." (PMID 38654325, 2024). "Heterogeneous nuclear ribonucleoprotein K (hnRNPK) plays a central role in regulating chemotherapy resistance across various tumor types." (PMID 39479349, 2024). "Together, these results demonstrated that HNRNPK promotes tumor growth, invasion and migration in vitro and in vivo." (PMID 36681772, 2023). "HnRNPK interacts with and stabilizes yes-associated protein (YAP) on target gene promoters in TNF-α-stimulated hepatic progenitor cells to promote tumor development." (PMID 36982162, 2023). "HnRNPC, hnRNPK, and hnRNPU induced the expression of the inflammatory nitric oxide synthase 2 (Nos2), an enzyme involved in tumor metastasis through the production of reactive oxygen species, in a bacteria-infected RAW264.7 mouse macrophage cell line." (PMID 36982162, 2023). "The results indicated that overexpression HNRNPK promoted tumorigenesis, as reflected by increased tumor size and tumor weight in the model." (PMID 36681772, 2023). "Ultimately, the rescue functional assays comprising CCK-8 proliferation assay and wound-healing assay were exploited to figure out that overexpressing hnRNPK eliminated LYPLAL1-DT-induced tumor suppressor effects in vitro." (PMID 38111678, 2023). "In cancer, overexpression of HNRNPK promotes tumor progression and correlates with poor patient survival, likely by directly affecting the expression and activities of oncogenes and tumor suppressors such as EIF4E, c-MYC, c-SRC and MDM2." (PMID 37592256, 2023). "Knockdown and overexpression HNRNPK cell as well as their control cells were delivered into nude mice, and tumor growth was monitored and compared." (PMID 36681772, 2023). "Meanwhile, the knockdown of HNRNPK significantly impaired tumor progression, as reflected by decreased tumor size and tumor weight in the model." (PMID 36681772, 2023). "A study found that hnRNPK is a conserved DNA/RNA binding protein that has a high expression level in tumor tissues and is closely related to the prognosis of malignant." (PMID 36964488, 2023). "This creates a consistent picture of SCFFbxo4 as critical regulator of tumor development affecting uncontrolled proliferation, senescence bypass (D1, Fxr1) and tumor progression (hnRNPK)." (PMID 36329064, 2022). "Taken together, although hnRNPK evidently plays an important role in cancer development, its function as an oncogene or a tumor suppressor gene remains debatable." (PMID 35352475, 2022). "This study suggested that HNRNPK/CLCN3 axis facilitated the LUAD progression through tumor cell interactions with CAFs." (PMID 36439880, 2022). "At the end of the experiment, the mean tumor volume and weight of the hnRNPK‐knockdown group was significantly smaller than that of the control group." (PMID 35352475, 2022).
tumor (continued). "Several studies have demonstrated that hnRNPK can regulate tumorigenesis and tumor suppressor pathways, overexpression, and knockdown expression." (PMID 35352475, 2022). "We discovered that a correlation existed between higher HNRNPK expression and deeper tumor invasion (P = 0.019), and a correlation between greater CLCN3 expression and an elevated probability of lymph node metastases (P = 0.027)." (PMID 36439880, 2022). "Subsequently, to observe the functional regulation of CLCN3 on tumor metastasis in vivo, stable HNRNPK-knockdown cells (H1299) and rescue model cells were transfected with luciferase plasmids and then injected into nude mice's tail veins." (PMID 36439880, 2022). "The key biological activities of CLCN3, which were reduced following HNRNPK downregulation and elevated following HNRNPK upregulation in vitro, demonstrate that HNRNPK performs a role in the promotion of tumor growth." (PMID 36439880, 2022). "HNRNPK and HNRNPL belong to the heterogeneous nuclear ribonucleoprotein family and interact with tumor-associated lncRNAs to regulate the tumorigenesis and progression of various cancers, including HCC." (PMID 36289466, 2022). "In the second group, when the tumor volume reached 50mm3, iAb‐hnRNPK vector and saline were intratumorally injected respectively every two days." (PMID 35352475, 2022). "Here we demonstrate that pro-tumorigenic activities of cytoplasmic hnRNPK are checked by the tumor suppressive function of Fbxo4." (PMID 36329064, 2022). "The tumor suppressive properties of SCFFbxo4 and oncogenic activity of hnRNPK dysregulation, suggest that SCFFbxo4 ubiquitylation in the cytoplasm inhibits hnRNPK cytoplasmic functions." (PMID 36329064, 2022). "We observed that the tumor weight and growth were significantly suppressed following HNRNPK knockdown, and the inhibitory influence was abrogated by CLCN3 overexpression." (PMID 36439880, 2022). "The role of hnRNPK in tumor development likely depends on tissue type and microenvironment, including recruitment of bound RNA, DNA, and proteins." (PMID 35352475, 2022). "It is likely that additional hnRNPK target mRNAs, as highlighted in our ribo-seq, contribute to regulation of tumor cell growth and are critical to maintain cell homeostasis." (PMID 36329064, 2022). "Together these observations demonstrate that according to the expected tumor suppressor nature of Fbxo4, SCFFbxo4 functions as a limiting factor for hnRNPK-mediated oncogenic translation." (PMID 36329064, 2022). "Recent studies have shown that hnRNPK is highly expressed in many human tumor cells, which is consistent with our previous findings that it plays an important role in tumorigenesis." (PMID 35352475, 2022). "FXR1, FXR2 and hnRNPK are required for these treRNA functions, while their expression promotes tumour invasion in vitro and metastasis in vivo." (PMID 34044876, 2021). "Then, the relative expression of HnRNPK mRNA, miR-206 and miR-613 in tumor tissue was verified by RT–qPCR." (PMID 34857003, 2021). "HNRNPK is a highly conserved RNA‐ and DNA‐binding protein and its dysregulation has been shown to correlate with tumor development, progression, and prognosis." (PMID 35284334, 2021). "We first provide experimental evidence demonstrating that the E3 ubiquitin ligase SPOP plays a critical tumor suppressive role in PrCa by specifically binding and promoting the degradation of HnRNPK via polyubiquitination." (PMID 34857003, 2021). "LncRNA 91H is known to play a prominent role in tumor development by enhancing tumor cell migration and invasion through the modification of heterogeneous nuclear ribonucleoprotein K (HNRNPK) protein expression." (PMID 33396739, 2020). "In epithelial tumors, HNRNPK interacts with Keratin 17 to promote tumor growth through inflammatory responses mediated through the CXCR3 and AIRE pathways." (PMID 31519929, 2019).
tumor (continued). "HNRNPK has been extensively studied for its role in tumorigenesis where it can act both as a tumor suppressor or oncogene depending on context." (PMID 31519929, 2019). "We established a new tumor cell line in which HNRNPK can be downregulated in a DOX‐dependent manner." (PMID 31942561, 2019). "HNRNPK has been prominently studied in cancer and has been described as both an oncogene and tumor suppressor." (PMID 31519929, 2019). "The biggest advantage of our newly established model is that HNRNPK is downregulated 1 week after tumor implantation, which, to a large extent, stimulates the clinical treatment process." (PMID 31942561, 2019). "In summary, our results suggested that lncRNA 91H was mainly transferred by exosomes which greatly enhanced tumor migration and invasion through modifying HNRNPK expression." (PMID 29410604, 2018). "HNRNPK is an RNA-binding protein which has been reported to be overexpressed in lots of cancers and involved in many tumor processes such as metastasis." (PMID 29410604, 2018). "Based on current knowledge, it is still difficult to define HNRNPK as an oncogene or a tumor suppressor gene because of dichotomous results from clinical association data and cell line studies." (PMID 29262567, 2017). "Other than that, Hnrnpk haploinsufficient mice are tumor prone and develop malignant phenotypes, suggesting HNRNPK plays a potential role in tumor suppression." (PMID 29262567, 2017). "In the current study, we demonstrate that up-regulation of miR-223 is potentially responsible for aberrant expression of hnRNPK in PDAC tumor cells." (PMID 28423622, 2017). "The size and weight of tumours from the hnRNPK knockdown group were significantly lower than that of the control group." (PMID 27862976, 2017). "Overexpression of hnRNPK is found in various cancers and has been correlated with poor prognosis, however, its action mechanism in tumor development and progression are largely under-explored." (PMID 28423622, 2017). "Overexpression of HNRNPK in GC cell lines displayed a significant reduction in proliferation, colony formation in vitro and tumor growth in vivo." (PMID 29262567, 2017). "Clinicopathological correlation analysis revealed positive correlation between elevated hnRNPK levels with poor differentiation and advanced tumour stage." (PMID 27862976, 2017). "Thus, HNRNPK has an important role in cell fate, governing the path toward neoplasia or senescence and aging." (PMID 40338663, 2025). "Finally, we established tumor models by employing 5–8 F cells expressing different levels of hnRNPK to comprehensively evaluate the impact of hnRNPK expression on cisplatin chemotherapy." (PMID 39479349, 2024). "In NPC tumor-bearing mice, hnRNPK knockdown enhances the efficacy of cisplatin chemotherapy." (PMID 39479349, 2024). "Significant tumor formation was observed 7 days after implantation with overexpressed HNRNPK (WT)." (PMID 39494331, 2024). "Critically, as a biomarker of tumor apoptosis induced by chemotherapy, hnRNPK promotes metastases in tumors by up-regulating MMP, which may explain the overexpression of hnRNPK in drug-resistant tumors." (PMID 39479349, 2024). "In addition, the present study revealed a mechanism by which lncRNAs can upregulate the expression of ATG2A by combining with hnRNPK, thus promoting autophagy and tumor growth." (PMID 37460467, 2023). "Overall, our findings suggest that the HNRNPK/CLCN3 axis might act as an important mediator of CAF-tumor interaction in LUAD progression." (PMID 36439880, 2022). "Additionally, in vivo rescue experiments were conducted to confirm that si-hnRNPK reversed the tumor metastasis promoter effect of CRLM1 in CRC cells." (PMID 35907898, 2022).
tumor (continued). "HNRNPK/CLCN3 axis facilitates the progression of LUAD through CAF-tumor interaction." (PMID 36439880, 2022). "The overall effect of hnRNPK knockdown on tumor growth was statistically significant." (PMID 35352475, 2022). "Recently, hnRNPK was also validated as a tumor suppressor in gastric and hematological tumors." (PMID 35875075, 2022). "Thus, HNRNPK has the potential to serve dual functions, either preventing or enhancing tumor growth, depending on the kind of tumor it is acting on." (PMID 36439880, 2022). "Moreover, translocation of hnRNPK into nucleus promotes tumor metastases by up-regulating matrix metalloproteinase." (PMID 35875075, 2022). "Moreover, SNORD126 activates the PI3K–AKT pathway in liver and colorectal cancer by combining with hnRNPK to promote tumor cell proliferation in vitro and tumor formation in xenograft models in vivo." (PMID 35790714, 2022). "As a transcription factor, hnRNPK binds to the eIF4E promoter region and 3′ untranslated region of p21 mRNA, inhibiting p21 translation and increasing translation initiation, cell division, and tumor formation." (PMID 35352475, 2022). "Moreover, HnRNPK has been shown to play a critical role in tumor progression by regulating metastasis and angiogenesis." (PMID 36038571, 2022). "SPOP is an adaptor protein of Cullin 3-based E3 ubiquitin complexes, has been shown to participate in diverse cellular processes and plays tumor suppressive roles in PrCa, suggesting that HnRNPK may be a substrate of SPOP." (PMID 34857003, 2021). "hnRNPK is an RBP containing three K homology domains (KH1, KH2 and KH3) and is closely associated with tumors. hnRNPK could play either a tumor suppressive or an oncogenic role in different types of cancer." (PMID 33623018, 2021). "Additionally, Qihong Huang identified a novel ribonucleprotein (RNP) complex (hnRNPK, FXR1, FXR2, PUF60, SF3B3), which is required for translational regulation of lncRNA to cause tumor invasion and metastasis." (PMID 34057025, 2021). "Then, the relative expression of HnRNPK mRNA in xenograft tumor tissue was verified by RT–qPCR." (PMID 34857003, 2021). "Notably, downregulation of HNRNPK was performed 1 week after tumor implantation by induction with doxycycline (DOX)." (PMID 31942561, 2019). "We established a new human tumor cell line with reduced expression of HNRNPK." (PMID 31942561, 2019). "However, hnRNPK expression was decreased in tissues from higher neoplasm histologic grades of GC (p = 0.03, Grade 3 and 4 vs. Grade 1and 2), suggesting that hnRNPK expression is positively correlated with well-differentiated GC cells." (PMID 31857793, 2019). "The clear impact of HNRNPK on tumor growth and differentiation suggests that HNRNPK under normal circumstances may be a potent regulator of tissue homeostasis." (PMID 31519929, 2019). "hnRNPK itself is a multifunctional protein that might regulate both oncogenic or tumor suppressive pathways through its diverse activates." (PMID 31857793, 2019). "We found that serum lncRNA 91H expression was closely related to cancer exosomes in vitro and vivo which may enhance tumor-cell migration and invasion in tumor development by modifying HNRNPK expression." (PMID 29410604, 2018). "HNRNPK was regulated by lncRNA 91H mediation so that it could further promote tumor development and metastasis." (PMID 29410604, 2018). "Furthermore, hnRNPK overexpression in UM‐UC‐3 cells by transfection revealed that hnRNPK upregulation promoted tumour cell growth and colony formation." (PMID 27862976, 2017).